ATM (ATM serine/threonine kinase)
Diseases named in the same sentence as ATM in open-access papers (continued):
Sharing a sentence is not in itself a finding about the gene and the disease.
prostate carcinoma (continued). "The HR/PARP synthetic lethality model may be more widely applicable in prostate cancer with germline or somatic inactivating mutations in the HR DNA repair genes, CHK2, BRIPI/FANCJ, NBS1, BRCA1, and ATM, collectively thought to occur in 20–25% of prostate cancer cases." (PMID 24616882, 2014). "Combining SBRT with DDR-targeted agents (e.g., ATM, DNA-PK, or PARP inhibitors) and immunomodulatory approaches holds promise for overcoming resistance and improving outcomes in prostate cancer." (PMID 40725389, 2025). "BRCA2 and BRCA1 also reached this level for ovarian cancer, BRCA2, ATM, and CHEK2 for prostate cancer, and ATM for pancreatic cancer." (PMID 40073867, 2025). "BAP1 alterations stood out in kidney (9.9%) and cervix (2.9%) cancers, with ATM most frequent in bladder cancer (7.7%), CDK12 notable in prostate cancer (7.4%), and FANCA prominent in melanoma (3.1%)." (PMID 40420266, 2025). "The TRITON-3 trial randomized patients with metastatic castrate resistant prostate cancer failing doublets hormonal therapy in the CS setting with BRCA 1, BRCA 2 or ATM alterations to rucaparib vs. physicians’ choice." (PMID 41430171, 2025). "As a next step, we performed a functional assay to establish the role of ATR/CHK1 and ATM/CHK2 pathways in the cell death induced by 6-TB and 7-TB in three human prostate cancer cell lines." (PMID 38783016, 2024). "In this study, we investigated the radiosensitising effects of three different DNA damage response inhibitors targeting ATM, ATR, and PARP in combination with X-rays and radium-223 on human prostate cancer cell lines." (PMID 38672592, 2024). "Seven genes (ATM, BCL2, ERN1, FOS, NRAS, PIK3R1, and SP1) were regulated in opposite directions in patients with HD and prostate cancer." (PMID 37298337, 2023). "It has been revealed that DDR genes alterations including BRCA2, BRCA1, CDK12, ATM, FANCD2, or RAD51C affect almost 20% of 333 primary prostate cancer." (PMID 36739400, 2023). "In a molecular analysis of 333 primary prostate cancers, the Cancer Genome Atlas (TCGA) study showed a 19% prevalence of alterations in several DNA repair genes, including BRCA2, BRCA1, ATM, CDK12, FANCD2, and RAD51C." (PMID 37240284, 2023). "In addition, among localized prostate cancers under active surveillance in the United States, prostate cancer patients with germline BRCA1/BRCA2 or ATM pathogenic variants were 1.96 times more likely to be upgraded on re-biopsy specimens than prostate cancer patients without pathogenic variants." (PMID 37174127, 2023). "Again, in line with data reported here, it has been recently shown that in cellular models of castration-resistant prostate cancer, MET inhibition enhances the efficacy of PARPi by suppressing the ATM/ATR and PI3K/AKT pathways." (PMID 35628590, 2022). "Germline BRCA2-altered prostate cancer patients had the highest HRD scores, germline ATM-altered patients had intermediate scores and germline CHEK2-altered patients had the lowest scores." (PMID 35740616, 2022). "ATM and the MMR pathway have previously been pointed out as potentially relevant for prostate cancer etiology and aggressiveness among men of African ancestry." (PMID 35079693, 2022). "For example, most hereditary cancer panels include genes for breast, ovarian and colon cancer – and includes the five main genes for prostate cancer discussed here (BRCA1, BRCA2, CHEK2, ATM, PALB2)." (PMID 35732815, 2022). "For likely pathogenic mutations, FANCM and FH ranked top for kidney cancer, RAD51C ranked top for bladder cancer, and ATM and PMS2 ranked top for prostate cancer." (PMID 36451132, 2022).
prostate carcinoma (continued). "Galiellalactone increases ATM/ATR, p-Chk1 (Ser345), and cyclin B1 protein levels in prostate cancer cells." (PMID 35651747, 2022). "Moreover, ATM signaling can also be upregulated in cancer cells that have already evaded cell apoptosis through other mechanisms, as seen in melanoma through upregulation of melanoma-associated antigen-encoding (MAGE) genes as well as in prostate cancer by activation of the Androgen receptor (AR)." (PMID 34068084, 2021). "For example, PARP inhibitors were FDA approved in prostate cancer with BRCA1/2 alterations and other homologous recombinational repair (HRR) genes such as ATM." (PMID 34200508, 2021). "For instance, DNA damage, ATM and Chk2 kinase activation, γH2AX nuclear foci formation and subsequent G2/M cell cycle arrest have been observed in SFN-treated prostate cancer cells." (PMID 32727075, 2020). "ATM/Chk2 pathway and ATR/CHk1 pathway is known to be DDR regulator in many cancers including prostate cancer." (PMID 32459662, 2020). "Among candidate prostate cancer genes, PV frequencies were highest for BRCA2 (3.8%), ATM (2.7%), and CHEK2 (2.5%)." (PMID 32439974, 2020). "In this study, we demonstrated that N-Myc confers prostate cancer cells the ADT-resistance and Enzalutamide-resistance by differentially regulating ATM pathways." (PMID 30657058, 2019). "For example, active phospho-ATM is co-localised with the hypoxic marker CAIX in tumour xenografts and RAD51 down-regulation was observed in cervical and prostate cancer xenografts as well as in a glioma model." (PMID 30943920, 2019). "AR antagonists induce telomere DNA damage in AR-positive LNCaP prostate cancer cells, and a DDR that has the features of a bona fide telomere DDR, namely, activation of ATM, as indicated by an increase in phosphorylated ATM (pATM) at telomeres." (PMID 31083651, 2019). "Recently, increased phosphorylation of ATM and CHK2 (CHK2pTHr68) was specifically found in the precursors of prostatic carcinoma." (PMID 18509505, 2008). "There were 5271 prostate cancer patients included with 18 (0.3%) having germline BRCA1 alterations, 139 (2.6%) with BRCA2 alterations, 49 (0.9%) with germline ATM alterations, 15 (0.3%) with germline PALB2 alterations, and 27 (0.5%) with germline CHEK2 alterations." (PMID 40361359, 2025). "In addition to breast and prostate cancer, the UKB analyses show a clear excess of other cancers with risks (approximately threefold) also higher than for ATM PTVs." (PMID 40451289, 2025). "In prostate cancer, the population without pathogenic variants in BRCA1/2, CHEK2, ATM and HOXB13E accounted for 98.0% of individuals and 95.8% of cases." (PMID 40016794, 2025). "In comparison, the efficacy of ATM inhibitors for the treatment of prostate cancer has not been extensively studied; however, there are three ATM inhibitors (M354, AZD0516, and AZD1390) undergoing clinical investigation." (PMID 38672592, 2024). "In addition, other frequently altered DDR genes in prostate cancer are BRCA1, ATM, CDK12, RAD51C, and FANCD2." (PMID 35205654, 2022). "In prostate cancer, NR2C2 could prevent or delay prostate tumorigenesis via regulating the ATM expression at the transcriptional level and could suppress prostate cancer invasion via altering the TIMP-1/MMP2/MMP9 signals." (PMID 34956884, 2021).
prostate carcinoma (continued). "Germline or somatic mutations in DNA damage repair (DDR) genes, such as BRCA2, CHEK2, ATM, RAD51D, BRCA1, and PALB2, have been described in around 20–25% of advanced prostate cancer patients, which involved in aggressive disease and poor outcomes in these patients." (PMID 33413230, 2021). "ATM expression was upregulated in kidney and liver cancers, but not in lung and prostate cancers, while it was downregulated in breast and uterine cancers." (PMID 32111912, 2020). "Importantly, the HRR abnormalities are observed in 31% of advanced prostate cancers and include: BRCA2 (9.8%), CDK12 (5.6%), ATM (5.2%), CHEK2 (1.8%), BRCA1 (1.4%) FANCA (1.3%), and ATR (1.1%)." (PMID 31366128, 2019). "Consequently, activated ACK1 promoted radioresistance of prostate cancer cells and conversely, a small molecule ACK1 inhibitor, e.g. AIM-100 blocks ATM dependent DNA damage induced G2/M arrest, resulting in the accumulation of cytotoxic DSBs." (PMID 26546517, 2015). "Intriguingly, unlike the non-malignant prostate epithelial cells, the ATM/ATR DNA damage checkpoint appears to be defective in prostate cancer cells, since androgen treatment only induced a partial activation of the DNA damage response." (PMID 23272087, 2012). "Interestingly, ATM has been reported to be highly activated in prostatic intraneoplasia (PIN), which is regarded as a precursor of prostate cancer." (PMID 23272087, 2012). "Indeed, in UKB European cohort, we found that 2.9% (48/1641) of all aggressive prostate cancer cases carried a BRCA2 or ATM QV compared to 0.9% (114/12,936) of non-aggressive prostate cancer cases (PFET = 1.46 × 10−10)." (PMID 39971927, 2025). "Consistently with previous reports, the frequency of alterations in AR and HRR genes including BRCA2 and ATM was enriched in mCRPC compared with mCSPC, suggesting that alterations in AR and HRR genes promote treatment resistance to initial ADT-based therapy in prostate cancer." (PMID 39516321, 2024). "In another study, it was discovered that patients with lethal PCa had a significantly higher combined rate of germline BRCA/ATM alterations than those with localized PCa, and those with local disease or a diagnosis of metastases had a shorter prostate-cancer-specific survival time than non-carriers." (PMID 37732318, 2023). "Although molecular alterations in HRR genes besides BRCA1/2 are less established surrogate markers for HRD, mutations in ATM and PALB2 but not in other HRR genes were shown to be associated with sensitivity to PARPi in prostate carcinoma in a phase 3 clinical trial." (PMID 36779660, 2023). "Therefore, patients with prostate cancer and pathogenic variants of BRCA1/BRCA2 or ATM are not appropriate candidates for active surveillance, even if other clinical and pathological features are acceptable." (PMID 37174127, 2023). "Thus, in prostate cancer cells eIF2α controls basal ATM and AMPKα protein levels and that in the absence of ATM or AMPK, the ability of the cell to cause eIF2α S51 phosphorylation is also diminished." (PMID 36408163, 2022). "Interestingly, previous research attested that the ATM protein level in prostate cancer cells was elevated compared to heathy samples, and activation of ATM in prostate intraepithelial neoplasia (PIN) was recognized as a precursor of prostate cancer." (PMID 35910852, 2022). "In addition, because apoptosis is not a predominant form of cell death after radiation in prostate cancer, it is unlikely to be the mechanism underlying LITAF's regulation of ATM described in this study." (PMID 29845714, 2018). "Similarly, GL induces apoptosis in androgen-insensitive prostate cancer cells through activation of ATM/ATR-CHK1 signaling without inducing DNA break." (PMID 26683224, 2016).
prostate carcinoma (continued). "Notably, knockdown of the ATM gene expression in HPr-1AR cells can promote androgen-induced TMPRSS2: ERG rearrangement, a prostate-specific chromosome translocation frequently found in prostate cancer cells." (PMID 23272087, 2012). "Moreover, growing evidence indicates that alteration of other major homologous recombination repair (HRR) proteins, such as ATM, may induce a response to PARP inhibitors in patients affected by multiple solid malignancies, such as prostate cancer and triple-negative breast cancer." (PMID 34201893, 2021). "It is of note that ATM KO did not significantly sensitize cells to PARPi in HEK293A cells, which is consistent with a recent report showing that ATM KO did not enhance PARPi efficacy in 3 prostate cancer cell lines." (PMID 34320214, 2021). "However, the absence of HRD in ATM-associated tumours does not exclude the possibility that HetAT subjects who develop BC may be sensitive to cisplatin and/or poly(ADP)-ribose polymerase (PARP) inhibitors, as reported by others for HetAT subjects who developed prostate cancer." (PMID 29665859, 2018).
ovarian carcinoma (217 papers, 2005 to 2026). A malignant neoplasm originating from the surface ovarian epithelium. "ESMO clinical guidelines affirm that for women carrying PALB2 P/LP variants the risk of ovarian cancer is 3–5% and that for ATM is likely 5%." (PMID 39984762, 2025). "We used cervical, breast, lung and ovarian cancer cells bearing mutations in BRCA1 or ATM and depleted SETD1A using siRNA or CRISPR/Cas9." (PMID 39994444, 2025). "We report two cases of ovarian cancer in individuals with germline pathogenic ATM variants, discussing the therapeutic strategies adopted." (PMID 39984762, 2025). "Several researchers have investigated the role of ATM mutations in the development of ovarian cancer." (PMID 39543654, 2024). "Heterozygosity for loss-of-function variants in ATM has been shown to be associated with an increased risk of development BC, as well as a significant risk of prostate, pancreatic, and ovarian cancers." (PMID 39684352, 2024). "They reported that ATM mutations as pathogenic variants were associated with three-fold increased risk of ovarian cancer (OR 2.85; 95% CI 1.30–6.32)." (PMID 39543654, 2024). "Their findings revealed a 2.4 risk of ovarian cancer associated with ATM mutations (OR = 2.4, 95% CI 1.2–4.4, p = 0.01) in the ExAC cohort." (PMID 39543654, 2024). "We aimed to investigate the GC-5′ss of the breast/ovarian cancer susceptibility genes, ATM (exon 50), BRIP1 (exon 1), and PALB2 (exon 12), and their dysregulation induced by DNA variants." (PMID 39518003, 2024). "Large studies in women with ovarian cancer have shown that there can be a slightly increased risk of ovarian cancer in carriers of ATM PGVs, but there is currently insufficient evidence to recommend risk-reducing salpingo-oophorectomy." (PMID 38672070, 2024). "BRCA1 and BRCA2 PVs confer increased risks of prostate, pancreatic, and ovarian cancers, while moderate-to-high risks of pancreatic (OR 4.21), prostate (OR 2.58), and gastric (OR 2.97) cancers were estimated for ATM-variant carriers." (PMID 38929805, 2024). "ATM mutations were linked to at least a small increased risk of ovarian cancer (OR 1.69, 95% CI 1.19–2.4, p = 0.0032)." (PMID 39543654, 2024). "Overall, these studies suggest that ATM mutation led to a modest increase in risk of ovarian cancer." (PMID 39543654, 2024). "Olaparide has a significant effect on both castration resistant prostate cancer (CRPC) and ovarian cancer patients with ATM mutation, and a multi‐center clinical trial called ORION has been carried out for olaparide in the treatment of advanced NSCLC." (PMID 36161776, 2023). "For example, PARP inhibitors sensitize ovarian cancer cells to ferroptosis by synergistically activating ATM/ATR and causing DNA damage." (PMID 37842240, 2023). "ATM germline PVs were estimated to moderately increase ovarian cancer risk, with an OR of 1.977 (95% CI, 1.33–2.94; p = 0.001)." (PMID 35008949, 2022). "Consensus guidelines for hereditary breast and ovarian cancer include management recommendations for pathogenic/likely pathogenic (P/LP) variants in ATM, CHEK2, PALB2, and other DNA damage repair (DDR) genes beyond BRCA1 or BRCA2." (PMID 35626031, 2022). "Women with disease-causing gene changes (faults/mutations) in BRCA1, BRCA2, PALB2, CHEK2 and ATM are at an increased risk of developing certain types of cancer—specifically breast (all genes) and epithelial ovarian cancer (only BRCA1, BRCA2, PALB2)." (PMID 35681696, 2022). "Ataxia telangiectasia mutated (ATM) is one the core molecules involved in the DNA damage response, and somatic mutations in ATM account for approximately 30% of the risk of developing different types of cancers, including ovarian cancer." (PMID 35795059, 2022). "For ATM, the prevalence of this mutation was 0.6% out of more than 1500 women with ovarian cancer reported to SEER registries." (PMID 35159349, 2022). "Abnormal expression of the ATM gene was reported to closely associate with poor prognosis in ovarian cancer patients." (PMID 33802884, 2021).